FOXP2 (forkhead box P2)
Diseases named in the same sentence as FOXP2 in open-access papers (continued):
Sharing a sentence is not in itself a finding about the gene and the disease.
prostate carcinoma (12 papers, 2014 to 2024). A carcinoma that arises from epithelial cells of the prostate gland. "To explore the molecular mechanism underlying the role of FOXP2 in prostate cancer, we first carried out analysis of the entire expression spectrum of 255 primary prostate tumors from TCGA." (PMID 37668356, 2023). "Aberrant levels of FOXP2 factor were found in different types of prostate cancers, strong levels being linked to poor prognosis in ERG fusion-negative prostate cancers." (PMID 29725501, 2018). "Among prostate cancers both loss and strong expression of FOXP2 was reported." (PMID 27224915, 2016). "In female zebrafish, Foxp2 deficiency leads to disruption of the HPG axis, and FOXP2 is overexpressed in human prostate cancer cells." (PMID 38752176, 2024). "(C) The significant enrichment of the 3206 FOXP2 expression-correlated genes (FECGs) in known prostate cancer gene sets from the Molecular Signatures database by gene set enrichment analysis (GSEA)." (PMID 37668356, 2023). "Conversely, the core members (HGF, MET, and PIK3CA) were downregulated in the FOXP2 knockdown PC3 prostate cancer cells." (PMID 37668356, 2023). "For instance, FOXP2 functions as an oncogene in colorectal cancer and diffuse large B-cell lymphoma but also acts as a suppressor in prostate cancer and gastric cancer." (PMID 36331719, 2023). "There was a statistically significant difference in the FOXP2 staining intensity between prostate cancer and benign prostate tissue (two-tailed p=0.001, by Fisher’s exact test)." (PMID 37668356, 2023). "In our study, we found a positive correlation between the expression of both MET and HGF and the expression of FOXP2 in prostate cancer tissues, FOXP2-overexpressing human prostate epithelial cells RWPE-1, and FOXP2-overexpressing NIH3T3 cells." (PMID 37668356, 2023). "The FOXP2 mRNA levels were significantly increased in prostate cancer samples with respect to normal tissues." (PMID 37668356, 2023). "Conversely, we carried out FOXP2 short hairpin RNA (shRNA) knockdown in two prostate cancer cell lines (LNCaP and PC3)." (PMID 37668356, 2023). "Conversely, FOXP2 silencing using shRNA caused decreases in phospho-MET and phospho-AKT levels in two prostate cancer cell lines, PC3 and LNCaP." (PMID 37668356, 2023). "For instance, miR-618 is downregulated in prostate cancer and suppresses cancer cell invasion and migration by targeting FOXP2." (PMID 35505304, 2022). "Conversely, overexpressed FOXP2 has been found in lymphomas, neuroblastomas, and prostate cancers, implicating a pro-oncogenic role of FOXP2 in these cancers." (PMID 33718155, 2021). "Transcriptomic analysis of twelve genes within the 4.12Mb region centered around FOXP2 in primary prostate cancer cells has uncovered a common trend towards severe down-regulation of this set of genes." (PMID 29725501, 2018). "To date, little is known regarding the link of FOXP2 to prostate cancer." (PMID 37668356, 2023). "Taken together, our data demonstrated that FOXP2 is tumorigenic in prostate cancer." (PMID 37668356, 2023). "Moreover, we explored the biological functions of FOXP2 in human prostate tumors and prostate cancer cell lines." (PMID 37668356, 2023). "Here, we investigated the expression of FOXP2 in prostate cancer samples." (PMID 37668356, 2023). "Likewise, FOXP2 expression was markedly elevated in human prostate cancer cell lines (PC3, LNCaP, VCaP, and DU145), but was undetectable or low in normal or immortalized human prostate epithelial cells (HPrEC and RWPE-1)." (PMID 37668356, 2023). "Conversely, FOXP2 knockdown suppresses the proliferation of prostate cancer cells." (PMID 37668356, 2023). "Furthermore, TLN2 hosts another microRNA, miR-132, which also targets FOXP2 transcripts, and has been widely reported as being involved during prostate cancer progression." (PMID 29725501, 2018). "However, to date, little is known regarding the link between FOXP2 and prostate cancer." (PMID 37668356, 2023).
prostate carcinoma (continued). "(E) The correlation analysis of gene expression between FOXP2 and MET signalling members in our primary prostate tumors (n = 92) and two other human primary prostate cancer datasets (GSE54460, n = 100; Taylor, n = 162) by qPCR." (PMID 37668356, 2023). "(N) Cell growth of prostate cancer cell lines (LNCaP and PC3) stably expressing control vector or FOXP2 shRNA (two clones, #1 and #2)." (PMID 37668356, 2023). "(I) Western blot measuring FOXP2 protein in one normal human prostate epithelial cell HPrEC and one benign prostate epithelial cell RWPE-1, and in three human prostate cancer cell lines, PC3, VCaP, and LNCaP." (PMID 37668356, 2023). "(H) Expression of FOXP2 mRNA in two types of human benign prostate epithelial cells, RWPE-1 and NPrEC, and in two prostate cancer cell lines LNCaP and DU145 from the GEO database (1555516_at)." (PMID 37668356, 2023). "There were no previous descriptions for the fusions NAIP:OCLN, PDE1C:DNAJC6, KANSL1:ARL17B, FOXP2:CREM, and AHSA1:DLG3 in the context of prostate cancer." (PMID 35625354, 2022). "Here, we found that FOXP2 is overexpressed in human prostate cancer cells and prostate tumors, but its expression is absent in normal prostate epithelial cells and low in benign prostatic hyperplasia." (PMID 37668356, 2023). "This miRNA has been shown to modulate metastasis in prostate cancer cell lines through the FOXP2 gene but not through TIMP-1." (PMID 30340564, 2018). "However, the FOXP2 expression pattern in normal prostate tissue and malignant neoplasms of the prostate has not been clearly characterized." (PMID 37668356, 2023). "The fusion of FOXP2 and CREM is novel and has not yet been associated with prostate cancer." (PMID 35625354, 2022). "This may activate different pathways and hormonal interactions compared with ERG fusion-negative prostate cancer leading to differential interactions with FOXP2 and distinctive tumor progression." (PMID 29725501, 2018). "In contrast, mutations of transcription factor FOXP2 were shown in neoplastic plasma cells and overexpression of FOXP2 is associated with high risk of early PSA recurrence in erythroblast transformation-specific-related gene (ERG) fusion-negative prostate cancers." (PMID 31815635, 2019). "In contrast, FOXP2 forkhead box P2 (FOXP2) and nibrin (NBN or NBS1) are overexpressed in fusion negative prostate cancer cells." (PMID 24739220, 2014). "Conversely, overexpressed FOXP2 has been reported in multiple myelomas, MGUS (Monoclonal Gammopathy of Undetermined Significance), several subtypes of lymphomas, as well as in neuroblastomas and ERG fusion-negative prostate cancers." (PMID 29725501, 2018).
gastric cancer (11 papers, 2018 to 2025). A primary or metastatic malignant neoplasm involving the stomach. "Like YY1, FOXP2 appears to play a dual function as an oncogene in several lymphomas, including multiple myeloma, and as a tumor suppressor in gastric cancer." (PMID 35409160, 2022). "For gene FOXP2, several researches have also reported the roles of FOXP2 as a tumor suppressor in gastric cancer and other diseases like osteosarcoma and hepatocellular carcinoma." (PMID 34322159, 2021). "Further, we identified 5 prognostic genes (RDH13, CLDN11, TMTC1, UCHL1, and FOXP2) in gastric cancer." (PMID 34322159, 2021). "For instance, miRNAs were reported to control the growth and apoptosis of gastric cancer cells by acting on FOXP2." (PMID 33117815, 2020). "We revealed that RDH13, CLDN11, TMTC1, UCHL1, and FOXP2 can serve as predictive biomarkers for gastric cancer treatment and the promoter methylation level of these five genes in serum could have prognostic and diagnostic functions in gastric cancer patients." (PMID 34322159, 2021). "Furthermore, miR-190-5p promotes cell migration and invasion by targeting FOXP2 in gastric cancer, suggesting a differential function of miR-190-5p possibly related to the specific disease context." (PMID 31624470, 2019). "Gastric cancer biopsies display mostly reduced FOXP2 immunoreactivity." (PMID 29725501, 2018). "Which factors may account for reduced FOXP2 expression level in gastric cancer remains to be determined." (PMID 29725501, 2018). "However, whether this event is oncogenic to or consequential from gastric cancer development, and whether and when other FOXP2-targeting miRs might be involved, remain two major issues to be solved." (PMID 29725501, 2018). "Another study demonstrated that miR-190-5p was increased in gastric cancer and functioned as an oncogene, which is based on the contribution of miR-190-5p to the proliferation of SGC7901 cells via targeting FOXP2." (PMID 31624470, 2019). "Established Human cells lines of the gastric cancer lineage have been shown to display reduced FOXP2 transcript levels when compared to non-cancerous gastric cells." (PMID 29725501, 2018).
neuroblastoma (10 papers, 2015 to 2025). Neuroblastoma (NB) is the most common solid, extracranial childhood tumor. "This may be related to the etiological event observed in glioblastoma and neuroblastoma associated with FOXP2 dysregulation, as a side-effect to its role in the acquisition of a stronger neurogenic contingent in the human brain." (PMID 29725501, 2018). "Follow‐up experiments confirmed that Foxp2 promotes neurite outgrowth in both mouse neuroblastoma cells and mouse striatal primary neurons." (PMID 34260143, 2021). "In early work on identifying targets of FOXP2, three studies performed ChIP‐chip experiments on human fetal tissue, human neuroblastoma cells, and embryonic mouse brain tissue." (PMID 34260143, 2021). "A ChIP‐sequencing study of FOXP2 in neuroectodermal tumor cells and neuroblastoma cells identified 58 targets near high‐confidence ChIP peaks from a merged dataset, that were mostly enriched for genes linked to transcriptional (regulatory) activity." (PMID 34260143, 2021). "Here, we investigate changes in FOXP2 expression in the SK-N-MC neuroblastoma human cell line after deletion by CRISPR-Cas9 of two enhancers located downstream of the gene." (PMID 31046704, 2019). "We have now proved that if FOXP2-Edistal is deleted, FOXP2 becomes downregulated and the levels of FOXP2 protein are reduced in the SK-N-MC neuroblastoma cells." (PMID 31046704, 2019). "SK-N-MC neuroblastoma cells derive from the supraorbital area and express FOXP2 and MDFIC constitutively." (PMID 31046704, 2019). "Retinoic acid treatment of human neuroblastoma cells induces neurite outgrowth and reduces cell migration, effects that are enhanced by concurrent FOXP2 overexpression, suggesting that the gene may modulate retinoic acid signaling in the developing brain." (PMID 34260143, 2021). "In neuroblastomas, multiple myelomas and several subtypes of lymphomas, FOXP2 is overexpressed." (PMID 31824836, 2019). "In order to provide an additional insight into its functional role we compared target gene expression levels between human neuroblastoma cells (SH-SY5Y) stably overexpressing FOXP2 cDNA of either humans or the common chimpanzee, Rhesus monkey, and marmoset, respectively." (PMID 28798667, 2017). "Kaplan-Meier plots showed a significant association between increased expression of CFHR3, MDFIC, CSMD3, FOXP2, or RALYL (genes with gains in coding regions) and poor OS in patients with neuroblastoma." (PMID 26159519, 2015). "While similar treatment of additional osteosarcoma lines induces FOXP2 transcripts, upregulation of FOXP2 protein is limited, and confluent growth arrest of the neuroblastoma line SH-SY5Y does not induce FOXP2 transcripts (data not shown)." (PMID 26034982, 2015). "As no FOXP2-ChIP studies have been performed on isolated cerebellar tissue, we focused on comparison with human neuronal studies, using human fetal brain and a human neuroblastoma cell line SH-SY5Y stably expressing FOXP2." (PMID 41236144, 2025). "On the other hand, overexpressed FOXP2 was reported in multiple myeloma, MGUS (Monoclonal Gammopathy of Unknown Significance) and in several subtypes of lymphoma (both RNA and protein or just in protein) as well as in neuroblastoma (RNA and protein)." (PMID 29725501, 2018).
developmental delay (9 papers, 2007 to 2024). "Various disruptions in the FOXP2 gene have been reported, and the conditions caused by said disruptions tend to include a broad spectrum of deficits, including: speech and language problems, verbal dyspraxia, low performance IQ, developmental delay, and brain abnormalities." (PMID 24765219, 2013). "Mice with homozygous Foxp2 disruptions display reduced postnatal weight gain, severe developmental delays, motor problems, and die at 3–4 weeks of age, demonstrating that Foxp2 is necessary for long-term survival." (PMID 27812326, 2016). "Vocalization differences in homozygous Foxp2 mutants co-occur with developmental delays, somatic weakness and general motor dysfunction, and are unlikely to represent direct effects." (PMID 20132318, 2010). "Oromotor and verbal dyspraxia and developmental delay in a child carrying a FOXP2 deletion." (PMID 24765219, 2013). "In conclusion, we have generated a conditional Foxp2 allele and shown that homozygous general deletion of exons 12–14 results in absence of Foxp2 protein, accompanied by developmental delays, severe motor dysfunction, and neural abnormalities." (PMID 17619227, 2007).
hepatocellular carcinoma (9 papers, 2016 to 2025). A malignant tumor that arises from hepatocytes. "FOXP2 is downregulated in tumor tissues of hepatocellular carcinoma; its downregulation remarkably promotes the invasiveness of hepatocellular carcinoma." (PMID 34335744, 2021). "The Human Protein Atlas suggests a moderate or weak expression level of FOXP2 in sections from hepatocellular carcinoma biopsies." (PMID 29725501, 2018). "Downregulation of FOXP2 also correlated with poor survival in hepatocellular carcinoma patients and enhanced cell invasiveness, reducing the expression of E-cadherin and increasing that of vimentin." (PMID 27224915, 2016). "Also, FOXP2 was downregulated in hepatocellular carcinoma (HCC) tumor tissues with poor overall survival rate and significantly promoted the invasiveness of HCC." (PMID 36203616, 2022). "Also, FOXP2 was downregulated in hepatocellular carcinoma (HCC) tumor tissues with poor overall survival rate and its downregulation significantly promoted the invasiveness of HCC." (PMID 31815635, 2019).
lymphoma (7 papers, 2018 to 2022). A malignant (clonal) proliferation of B- lymphocytes or T- lymphocytes which involves the lymph nodes, bone marrow and/or extranodal sites. "FOXP2 is considered to play an antitumour role in a variety of lymphomas, such as multiple myeloma, gastric cancer and liver cancer." (PMID 35281860, 2022). "Previous study found that miR-376a-5p expression was reduced in lymphoma and miR-376a-5p knockdown enhanced lymphoma proliferation and apoptosis by targeting FOXP2." (PMID 35201476, 2021). "Likewise, miR-181d-5p, miR-374b-5p, miR-122, miR-150 and miR-504 act as a tumor suppressor by inhibition of FOXP1, while miR-376a and miR-139 work as a tumor suppressor via inhibition of FOXP2 in lymphoma and osteosarcoma." (PMID 31815635, 2019).
osteosarcoma (7 papers, 2015 to 2025). A usually aggressive malignant bone-forming mesenchymal neoplasm, predominantly affecting adolescents and young adults. "Critically, we demonstrate that in 143B osteosarcoma cells with minimal endogenous expression, FOXP2 induced by growth arrest is required for up-regulation of p21WAF1/CIP1." (PMID 26034982, 2015). "Our data are consistent with a model in which transient upregulation of Foxp2 in pre-osteoblast mesenchymal cells regulates a p21-dependent growth arrest checkpoint, which may have implications for normal mesenchymal and osteosarcoma biology." (PMID 26034982, 2015). "Here we report a requirement for FOXP2 in growth arrest of the osteosarcoma cell line 143B." (PMID 26034982, 2015). "In addition, FOXP2 is essential for regulation of p21 in 143B osteosarcoma cell growth inhibition." (PMID 31815635, 2019). "Furthermore, FOXP2 status in osteosarcoma may provide information regarding the stage of developmental block, with potential clinical significance." (PMID 26034982, 2015). "In accordance with this hypothesis we demonstrate that FOXP2 is required for regulation of p21WAF1/CIP1 and growth-factor deprivation induced growth arrest of pre-osteoblast type 143B osteosarcoma cells." (PMID 26034982, 2015).
apraxia of speech (6 papers, 2014 to 2026). "Mutations of FOXP2 in 7q31 cause a rare disorder involving speech apraxia, accompanied by expressive and receptive language impairments." (PMID 26300977, 2015). "Interestingly, chronic activation of vmPFC neurons not only increases Foxp2, a gene implicated in childhood speech apraxia, but also Vglut1-labeled synapses in the striatum, suggesting that activity-dependent increases in Foxp2 may promote corticostriatal synaptogenesis." (PMID 42156914, 2026). "To illustrate, consider FOXP2, an autosomal dominant transcription factor that has been linked to the Mendelian disorder verbal dyspraxia SPCH1, and so a gene apparently necessary, but crucially not sufficient, for human speech, let alone language." (PMID 24847300, 2014). "PLAUR is a target of FOXP2 too, but also an effector of SRPX2, another of FOXP2’s targets and a candidate for speech dyspraxia." (PMID 30971880, 2019).
attention deficit-hyperactivity disorder (6 papers, 2020 to 2024). A disorder characterized by a marked pattern of inattention and/or hyperactivity-impulsivity that is inconsistent with developmental level and clearly interferes with functioning in at least two settings (e.g. at home and at school). "Neuronal phenotypes associated with FOXP2 mutations include expressive and receptive language impairment, orofacial dyspraxia, abnormalities in cortex, and basal ganglia as well as attention deficit hyperactivity disorder (ADHD)." (PMID 36581877, 2022). "Of course, we know that older children can have language disorders, including attention deficit hyperactivity disorder (ADHD) and autism spectrum disorder (ASD;), which may involve altered regulatory networks of genes relevant for language, including the transcription factor FOXP2." (PMID 37626546, 2023).